RNASET2 (ribonuclease T2)
Diseases named in the same sentence as RNASET2 in open-access papers (continued):
Sharing a sentence is not in itself a finding about the gene and the disease.
cancer (25 papers, 2009 to 2025). A tumor composed of atypical neoplastic, often pleomorphic cells that invade other tissues. "Taken together, this evidence supports the close association of RNASET2 with human cancer from multiple perspectives." (PMID 37679715, 2023). "Our evidence suggests that RNASET2 expression is upregulated in ccRCC tissues and cell lines and is associated with malignant behavior of cancer cells and poor prognosis of patients." (PMID 37679715, 2023). "Here, we found that mRNA expression of RNASET2 was closely associated with immunosuppressive checkpoints in a variety of human cancer tissues." (PMID 37679715, 2023). "In this study, missense substitution was the most common type of mutation in RNASET2 among 281 cancer samples, present in 75 (26.69%); synonymous substitution was present in 26 cases (9.25%)." (PMID 37679715, 2023). "Given the close association of RNASET2 with angiogenesis in other cancers, we explored its impact on this malignant phenotype of ccRCC." (PMID 37679715, 2023). "The human RNASET2 gene encodes for an evolutionarily conserved, pleiotropic extracellular ribonuclease, whose secretion by cancer cells in the tumor microenvironment (TME) is likely involved in tumor suppression." (PMID 32197460, 2020). "Future research could focus on elucidating the specific molecular pathways and genetic backgrounds associated with RNASET2 in different cancers." (PMID 38576019, 2024). "Interestingly, RNASET2 has been shown to be involved in cancer suppression and loss of function mutation causes cystic leukoencephalopathy." (PMID 28730546, 2017). "We also demonstrated that misexpression of the levels of TMEM230 and RNASET2 contributed to aggressive cancer features, including aberrant angiogenesis and destructive tissue remodeling, and a loss of normal cell-to-cell and cell-to-substratum attachments." (PMID 40141059, 2025). "In the current study, there is a correlation between MTA2 expression and RNASET2 expression, as well as cancer cell migration in ccRCC cells." (PMID 36728187, 2023). "First, we analyzed the expression of RNASET2 in human cancers and normal tissues based on the TCGA dataset." (PMID 37679715, 2023). "Human RNASET2 acts as a powerful oncosuppressor protein in in vivo xenograft-based murine models of human cancer." (PMID 32197460, 2020). "It has been previously shown that RNASET2 affects several important cancer-related parameters (such as modulation of cell proliferation, cytoskeletal re-organization, cell adhesion, motility, and angiogenesis) in a cell-autonomous manner." (PMID 32197460, 2020). "The in vitro cell proliferation rate and in vivo tumor growth rate in syngeneic BALB/c mice were thus evaluated for FL Rnaset2, E vector, and P untransfected cancer cells." (PMID 32197460, 2020). "Taken together, these results indicate that overexpression of murine Rnaset2 in a colon syngeneic mouse carcinoma model leads to a concerted anti-tumor immune response able to exert a tumor growth delay and rejection." (PMID 32197460, 2020). "In this manuscript, we have defined the oncoppressor RNASET2 gene as a new player in the control of the aberrant interaction between cancer cells and ECM." (PMID 30813308, 2019). "RNASET2 is an extracellular ribonuclease endowed with a marked antitumorigenic role in several carcinomas, independent from its catalytic activity." (PMID 30813308, 2019). "Noteworthy, these two parameters were increased in RNASET2-silenced OVCAR3 cells also in the absence of stress, suggesting that even under optimal culture conditions high RNASET2 expression levels can substantially affect several cancer-related parameters." (PMID 25797262, 2015). "Specifically, a wide range of cancer-related parameters, such as cell proliferation, clonogenic potential, anchorage-independent growth, and cell adhesion/invasion, have been reported to be negatively regulated by RNASET2 in several in vitro cellular models." (PMID 40389981, 2025).
cancer (continued). "RNASET2 has also been involved in dendritic cell (DC) maturation, highlighting its potential role in innate immunity, and extracellular secreted RNASET2 can inhibit a well-established cancer-promoting process such as angiogenesis." (PMID 40389981, 2025). "The reason why misexpression of the levels of TMEM230 and RNASET2 occurs in certain cancers is unknown to us." (PMID 40141059, 2025). "Additionally, 18 CCC, 5 HGSC and 12 MC HSGs had OncoScore > 50, among these were candidate cancer biomarkers such as RNASET2 for CCC, AKR1B10 for HGSC, and KRT20 for MC." (PMID 40390000, 2025). "Indeed, RNASET2 is involved in several human pathologies, including cancer, and it is functionally relevant in the TME." (PMID 34299186, 2021). "Besides its nuclease activity, RNASET2 exerts many additional functions and it has been involved in several human pathologies, including inflammation and cancer." (PMID 34299186, 2021). "Furthermore, 366 cases of GAC from TCGA Stomach Cancer database proved that the RNASET2 mRNA expression level was lower in advanced GAC (TNM IB, II, III, IV) than that in early GAC (TNM IA) (p = 0.001)." (PMID 32528897, 2020). "Recently, a new mode of action of this protein was assessed that led to the hypothesis that RNASET2 may affect cancer growth by affecting the ECM/integrin signaling pathway as well." (PMID 30813308, 2019). "We then asked whether certain cancer-related parameters were affected in vitro following RNASET2 modulation in both cellular models." (PMID 30813308, 2019). "This may lead to plan shorter and more effective molecules than the native human RNASET2, to improve its anti-angiogenic and anti-carcinogenic effects in cancer therapy." (PMID 25426551, 2014). "It will be of interest in future studies to define whether RNASET2 derived from cancer cell, could influence, the NK-κB pathway by changing the RELB expression levels in cells of the monocyte/macrophage lineage." (PMID 21646684, 2011). "Indeed, this finding contradicts our conventional knowledge of RNASET2 in human cancers and the reasons for this paradox are still unknown." (PMID 37679715, 2023). "The role of ribonuclease T2 (RNASET2) in HCC is still uncertain, although it has been reported to have contradictory effects on some cancers." (PMID 39903758, 2025). "To further explore the correlation between RNASET2 and the prognosis of GAC patients, we utilized TCGA Stomach Cancer database to perform survival analysis." (PMID 32528897, 2020). "While our findings expand the spectrum of cancer types responsive to RNASET2, the lack of effect observed in PC-3 cells highlights the existence of RNASET2 resistance mechanisms, warranting further investigation." (PMID 40389981, 2025). "The role of RNASET2 is not restricted to cancer cells and could be relevant also in other cell types which are important players in the TME." (PMID 34299186, 2021). "RNASET2 functions are not restricted to cancer cells and its expression could be relevant also in other cell types which are important players in the TME, including DCs." (PMID 34299186, 2021). "Finally, two genes that were up-regulated by RNASET2 were also selected for validation: LMCD1, belonging to the category of the LIMD1 tumor suppressor gene, and DSE (dermatan sulfate epimerase), whose protein product elicits specific cytotoxic T lymphocytes responses in cancer patients." (PMID 21646684, 2011). "RNASET2 has emerged as a multifaceted tumor suppressor gene (TSG), known to exert both cell-autonomous and non-cell-autonomous effects in several cancer types." (PMID 40389981, 2025).
infection (7 papers, 2016 to 2025). The state of being infected such as from the introduction of a foreign agent such as serum, vaccine, antigenic substance or organism. "The function of RNASET2 in stress, infection or injury is necessary to prevent pathogen cell replication and intracellular buildup of toxic or cell-damaging “free” RNA." (PMID 40141059, 2025). "RNASET2 is thought to inhibit pathogen colonization at infection sites." (PMID 39075348, 2024). "Additionally, RNASET2, a lumen component of lysosomes, was previously identified by our group to have a role in the immune system through its role in the recycling of cellular debris and components following injury, disease or infection." (PMID 40141059, 2025).
adenocarcinoma (1 paper, 2020). A common cancer characterized by the presence of malignant glandular cells. "Next, we downloaded the entire TCGA Stomach Adenocarcinoma (TCGA, Nature 2014) dataset, including the mRNA expression value of 29,505 genes, and performed a GSEA to analyze the potential relationship between RNASET2 mRNA expression and curated gene sets (C2) in the MSigDB." (PMID 32528897, 2020).
neurodegenerative disease (1 paper, 2021). A disorder of the central nervous system characterized by gradual and progressive loss of neural tissue and neurologic function. "Together, these reports indicate that FBXO6 might also be involved in the development of neurodegenerative diseases at least by regulating the stability of RNASET2 protein." (PMID 33767133, 2021).
RNASET2 also shares sentences with these, for which no sentence is quoted: acute lymphoblastic leukemia (3 papers); colorectal cancer (2); Hashimoto thyroiditis (2); inflammatory bowel disease (2); lymphoma (2); mammary adenocarcinoma (2); ulcerative colitis (2); amyloidosis diseases (1); asthenozoospermia (1); astrocytomas (1); atherosclerosis (1); autoimmune thyroiditis (1); bacterial infection (1); basal cell carcinoma (1); childhood asthma (1); diabetic nephropathy (1); glioma (1); Hyperglycemia (1); Hyperinsulinemia (1); hyperlipidemia (1); hyperthyroidism (1); hypothyroidism (1); immune diseases (1); Impaired glucose tolerance (1); lipid metabolic disorders (1); lymph node metastasis (1); Lysosomal disease (1); metabolic disorder (1); Multiple Myeloma (1); myeloid leukemia (1).
A further 7 diseases each share a sentence with RNASET2 in 1 paper.